RNU6-1014P (RNA, U6 small nuclear 1014, pseudogene)
Gene: Small nuclear RNA gene on chromosome 15 (46,660,658 to 46,660,760, forward strand). Ensembl gene ENSG00000238456.
Homologues: Orthologues: chimpanzee U6 (99% identical), pig U6 (76% identical). Paralogues in human: RNU6-140P (84% identical), RNU6-144P (84% identical), RNU6-38P (84% identical), RNU6-637P (84% identical), RNU6-1029P (83% identical), RNU6-1038P (83% identical), RNU6-1040P (83% identical), RNU6-1124P (83% identical), RNU6-116P (83% identical), RNU6-1316P (83% identical), RNU6-16P (83% identical), RNU6-25P (83% identical), and 1290 more.